CYC1 (cytochrome c1)
Description:
Component of the ubiquinol-cytochrome c oxidoreductase, a multisubunit transmembrane complex that is part of the mitochondrial electron transport chain which drives oxidative phosphorylation. The respiratory chain contains 3 multisubunit complexes succinate dehydrogenase (complex II, CII), ubiquinol-cytochrome c oxidoreductase (cytochrome b-c1 complex, complex III, CIII) and cytochrome c oxidase (complex IV, CIV), that cooperate to transfer electrons derived from NADH and succinate to molecular oxygen, creating an electrochemical gradient over the inner membrane that drives transmembrane transport and the ATP synthase. The cytochrome b-c1 complex catalyzes electron transfer from ubiquinol to cytochrome c, linking this redox reaction to translocation of protons across the mitochondrial inner membrane, with protons being carried across the membrane as hydrogens on the quinol. In the process called Q cycle, 2 protons are consumed from the matrix, 4 protons are released into the intermembrane space and 2 electrons are passed to cytochrome c. Cytochrome c1 is a catalytic core subunit containing a c-type heme. It transfers electrons from the [2Fe-2S] iron-sulfur cluster of the Rieske protein to cytochrome c.
Synonyms: UQCR4; MC3DN6
Tractability: Small molecule: a structure with a bound ligand is known. Antibody: UniProt predicts a signal peptide or a membrane-spanning region. PROTAC: ubiquitination databases record sites on it; its protein half-life has been measured; a small molecule that binds it is known.
Gene: Protein-coding gene on chromosome 8 (144,095,039 to 144,097,525, forward strand). Ensembl gene ENSG00000179091.
Subcellular location: Mitochondrion inner membrane
Subcellular location (Human Protein Atlas): Mitochondria; Equatorial segment
Pathways (Reactome):
Metabolism: Complex III assembly; Respiratory electron transport
Protein localization: Mitochondrial protein import
Gene Ontology:
Molecular function: protein binding; quinol-cytochrome-c reductase activity; electron transfer activity; heme binding
Biological process: cellular respiration; mitochondrial electron transport, ubiquinol to cytochrome c; proton transmembrane transport; response to glucagon
Cellular component: membrane; mitochondrial inner membrane; mitochondrion; nucleus; respiratory chain complex III
Genetic constraint (gnomAD): Loss-of-function variants: 9 observed, 26.93 expected, observed/expected ratio (o/e) 0.33, 90% interval 0.2 to 0.58. The upper end of that interval is the gene's LOEUF score, 0.58, which puts it in group 2 of 6, group 1 being the genes least tolerant of losing a copy. Missense variants: 417 observed, 384.43 expected, observed/expected ratio (o/e) 1.08, 90% interval 1 to 1.18. Synonymous variants: 196 observed, 158.95 expected, observed/expected ratio (o/e) 1.23, 90% interval 1.1 to 1.39.
Gene-disease validity (ClinGen):
ClinGen rates the evidence that CYC1 causes each of these diseases.
mitochondrial disease (autosomal recessive): Moderate.
Homologues: Orthologues: chimpanzee CYC1 (99% identical), macaque CYC1 (94% identical), pig CYC1 (86% identical), guinea pig CYC1 (85% identical), mouse Cyc1 (84% identical), rat Cyc1 (84% identical), tropical clawed frog cyc1 (64% identical), zebrafish cyc1 (61% identical), Drosophila melanogaster Cyt-c1 (49% identical), Drosophila melanogaster Cyt-c1L (45% identical), Caenorhabditis elegans cyc-1 (39% identical).